STAT3 (signal transducer and activator of transcription 3)
Diseases named in the same sentence as STAT3 in open-access papers (continued):
Sharing a sentence is not in itself a finding about the gene and the disease.
colon carcinoma (continued). "The change of myeloid-related HCK expression owing to STAT3 activation can regulate cancer-associated macrophage polarization and the growth of colon cancer." (PMID 33162805, 2020). "In colon cancer, the association between p-STAT3 and survival varies according to the study, but a high p-STAT3/p-STAT5 ratio indicates bad prognosis." (PMID 31557897, 2019). "The elucidation of the cellular and molecular mechanisms underlying the enhancement of colon cancer stemness downstream of the IL-6/STAT3/FRA1 signaling axis opens novel opportunities to develop alternative and possibly more effective therapeutic strategies." (PMID 30804456, 2019). "As we known, STAT3 is an important transcription factor which is essential in maintenance of the stem cells stemness and is also closely associated with colon cancer." (PMID 30962766, 2019). "In colon cancer, STAT3 activation is associated with an increased proliferation rate, tumour growth, and a reduced survival." (PMID 30850580, 2019). "Our immunohistochemical results showed that HBD reduced the expression of JAK2 and P-STAT3 associated with the IL-6/STAT3 signaling pathway and inhibited the formation of tumor cells in colitis-associated colon cancer." (PMID 30832202, 2019). "Immunohistochemical analysis indicated that there were less phosphorylated STAT3-positive cells in colon tumors of TRIM27-deficient mice compared to their wild-type littermates." (PMID 30143645, 2018). "For example, the IL-6 family of proinflammatory cytokines and their downstream effector STAT3 are important regulators in colitis-associated colon cancer, and the STAT3 signaling pathway contributes to inflammation-associated gastric carcinogenesis." (PMID 29849601, 2018). "As previously noted, colon cancer formation associated with enterotoxigenic B. fragilis has been shown to involve Stat3-driven colitis and induction of a Th17 response that was prevented by IL-17 and IL-23 blockade in mouse models." (PMID 29780391, 2018). "Owing to above results on the highly positive association of Anxa 2 and STAT3 with the invasion and migration of Caco-2 cells, we concluded that Anxa 2 coordinated STAT3 to regulate the invasion and migration in colon cancer cells." (PMID 27274723, 2016). "Conversely, IEC-specific Socs3 ablation or expression of the SOCS3-binding deficient gp130Y757F mutation both inducing STAT3 activation, promoted colonic tumor growth and incidence." (PMID 27582544, 2016). "We determined that STAT3 and nuclear pRKIP are significantly associated with poor patient prognosis in stage II colon cancer patients." (PMID 24098947, 2013). "We extended these observations and determined that that STAT3 and nuclear pRKIP are associated with poor patient prognosis in stage II colon cancer patients." (PMID 24098947, 2013). "In this study we demonstrate that the Janus family tyrosine kinase (Jak)-STAT3 pathway modulates bufalin-induced apoptosis in SW620 colon cancer cells and affects livin, caspase-3, BCL2-associatedX protein (BAX) expression." (PMID 23110625, 2012). "Consistently, in IL-17A-knockout mice STAT3 activation was markedly reduced compared with wild-type mice, and this associated with the development of fewer and smaller colonic tumors." (PMID 23109839, 2012). "Consistently, in the AOM + DSS model, mice with deletion of SOCS3 in intestinal epithelial cells show increased STAT3 and NF-κB activation and enhanced susceptibility to developing colonic tumors following AOM + DSS treatment." (PMID 23109839, 2012). "Moreover, there are variations in the association between p-STAT3 and survival in colon cancer, but a high p-STAT3/p-STAT5 ratio indicates a bad prognosis." (PMID 39136000, 2024). "In addition, interleukin 22 activates STAT3 in colon cancer cells to cause the autocrine production of CXCL3, which enhances chemotherapeutic resistance in tumor cells." (PMID 39201782, 2024).
colon carcinoma (continued). "IL-6 is also involved in signaling and immunoregulatory cascades by binding to its receptor (IL-6R) on gp130-positive cells – thereby activating the transcription factor signal transducer and activators of transcription 3 (STAT3) and increasing the risk of colon cancer." (PMID 36792680, 2023). "In line with this, the analysis of the association of JAK-1 and STAT-3 protein levels with the clinicopathological parameters of patients with colon cancer has demonstrated that the expression of these two proteins is associated with the clinical stage of the pathology." (PMID 36982677, 2023). "Jin and co-workers reported that orlistat could alleviate colon cancer induced by western diet-associated colitis via suppression of STAT3 and NF-κB signaling pathways." (PMID 37416772, 2023). "Therefore, we postulate that mutations in the DNA-binding domain of STAT3 or the novel downstream genes that are upregulated by the mutant STAT3 are potential biomarkers for colon cancer diagnosis." (PMID 33535185, 2021). "Besides Wnt/β-catenin pathway activation, aberrations in the homeostatic function of Nrf2, NF-κB and STAT3 signaling pathways are also considered important causative factors implicated in colon cancer development." (PMID 34443375, 2021). "However, few reports have investigated the efficacy of EGCG on STAT3 expression and clarified the underlying mechanisms against primary and metastatic colon-cancer cells." (PMID 33747527, 2021). "It has also been shown that protease-activated receptor 2 (PAR2) deficiency significantly promotes tumor development in the AOM/DSS-induced colitis-associated colon cancer model through accumulation of MDSCs and enhancement of their immunosuppressive activity via STAT3-mediated ROS production." (PMID 33384962, 2020). "Furthermore, hyperactivation of STAT3 is linked to abnormal differentiation of dendritic cells in colon cancer cells." (PMID 31684858, 2019). "In the mouse B16 tumor model, activated S1PR1 can accelerate tumor progression by activating STAT3 and upregulating IL-6, and this relationship between S1PR1 and STAT3 has been shown to contribute to chronic intestinal inflammation and colitis-associated colon cancer." (PMID 31807117, 2019). "Consistently, in both models of inflammatory bowel disease and colitis-associated colon cancer, mice exhibited reduced NFκB activation and STAT3 activation, which has been linked to increased epithelial proliferation, and decreased expression of pro-inflammatory cytokines and chemokines." (PMID 30544686, 2018). "Finally, the reported observation that Fondanol activates 15-LOX is interesting since, when overexpressed, this enzyme suppresses colitis-associated colon cancer through inhibition of the IL-6/STAT3 signaling pathway." (PMID 29710854, 2018). "In addition, both SAMe and MTA can lower IL-6 expression and inhibit IL-6/STAT3 signaling in a colitis-associated colon cancer model and in human colon cancer cells." (PMID 29108270, 2017). "Thus, we believe that FTD‐induced activation of ERK/AKT/STAT3 plays a similar role in the adaptive response of colon cancer cells to genotoxic stress caused by FTD." (PMID 28486761, 2017). "STAT3 is significantly associated with poor prognosis in stage II colon cancer patients." (PMID 28725043, 2017). "Since SAMe and MTA inhibited IL-6/STAT3 signaling in the colitis-associated colon cancer model and this pathway was shown to be critical for cancer invasion and metastasis, we examined whether SAMe and MTA might inhibit cancer cell migration." (PMID 29108270, 2017). "STAT3 activation induced by IL-6 via JAK has been implicated in colitis-associated colon cancer." (PMID 27589954, 2016). "For example, several research groups have demonstrated that phosphoinositide 3-kinase (PI3K/Akt), mitogen-activated protein kinase (MAPK) and signal transducer, and activator of transcription 3 (STAT3) pathways were activated in obesity-associated colon cancer." (PMID 23339750, 2013).
colon carcinoma (continued). "Inflammation-induced carcinogenesis pathways have been observed in colon cancer caused by enterotoxic Bacteroides fragilis which secretes a toxin that induces colitis by activating Signal Transducer and Activator of Transcription 3 (STAT3), a pathway involved in tumor formation." (PMID 40927726, 2025). "In addition, STAT3 is a critical IL-6 effector that induces colitis-associated colon cancer." (PMID 35372504, 2022). "Consistently, the protein levels of STAT3 downstream target genes Bcl-xl, c-Myc, Pcna, and Ccnd1, which were responsible for tumor cell survival and proliferation, respectively, were dramatically downregulated in colon tumors of TRIM27-deficient mice compared to their wild-type littermates." (PMID 30143645, 2018). "However, the mechanism underlying STAT3 inhibition in colon cancer is not clearly understood." (PMID 26824417, 2016). "Interestingly, STAT-3 phosphorylation is implicated in HCT-116 colon cancer cell growth." (PMID 26418031, 2015). "The increased secretion of IL-6 by MUC2-knockdown tumor cells and enhanced tumor growth observed in the present study suggest that the protective mechanisms of MUC2 in colon cancer may be associated with its effects on suppressing the IL-6/STAT3 signaling pathway." (PMID 25322805, 2014). "In this work, we designed and synthesized Ir-ART, a half-sandwich iridium based STAT3 inhibitor, for colon cancer therapy." (PMID 39697768, 2025). "An artesunate-modified half-sandwich iridium(iii) complex inhibits colon cancer cell proliferation and metastasis through the STAT3 pathway." (PMID 39697768, 2025). "Here, to inhibit the STAT3 pathway and suppress metastasis in colon cancer cells, the half-sandwich iridium complex Ir-ART containing an artesunate-derived ligand was synthesized." (PMID 39697768, 2025). "The NF-κB/STAT3 signaling pathway has been extensively investigated in relation to colon cancer, and it is widely acknowledged that this pathway plays a pivotal role in the pathogenesis of the disease." (PMID 40487290, 2025). "Due to the high expression of STAT3 in colon cancer, Ir-ART demonstrates the best anti-proliferation ability in HCT-116 colon cancer cells." (PMID 39697768, 2025). "The activation of NF-κB and STAT3 subsequently promoted the proliferation, invasion, and migration of colon cancer cells by clone formation assays, transwell assays, and scratch-wound assays." (PMID 40487290, 2025). "Herein, we focused on colon cancer to figure out the remedial impacts related to the secretome of MSCs (as a new strategy) through EGFR/c-Src/IRSp53/p-AKT/p-Stat3/cyclin D1 signaling pathway." (PMID 41200137, 2025). "Ultimately, a deeper understanding of TNF-α signaling and its interactions with other oncogenic pathways, such as NF-κB, Wnt/β-catenin, and STAT3, will pave the way for more effective and personalized treatments for colon cancer." (PMID 40558596, 2025). "NF-κB enhances the phosphorylation of STAT3, thereby activating the NF-κB/STAT3 signaling pathway in colon cancer." (PMID 40487290, 2025). "This study not only provides a novel metal-Cp*-based STAT3 inhibitor chemoimmunotherapeutic agents for treating colon cancer, but also further highlights the efficacy of the metal–ligand synergetic enhancement strategy in cancer treatment." (PMID 39697768, 2025). "Studies have shown that CAFs transformed by cancer cells within the TME secrete interleukin-6 and enhance STAT3 signaling in colon cancer cells, promoting the production of CSCs and further driving the progression of malignant tumors." (PMID 41194856, 2025). "Capsaicin, ouabain, and lycopene show their anticancer potential through the STAT-3 pathway in breast, colorectal, pancreatic, lung, cervical, ovarian and colon cancers." (PMID 39835210, 2025). "Nuclear phosphorylated STAT3 is known to regulate the DNMTs in hematopoietic cancer and colon cancer by binding to DNMT promoters to activate their expression." (PMID 40427627, 2025).
colon carcinoma (continued). "The overexpression of mCRPs in colon cancer leads to the upregulation of STAT3/STAT6/p38 MAPK signaling." (PMID 38671854, 2024). "Numerous studies have underscored the pivotal role of the IL‐6/STAT3 pathway in the transition from colitis to colon cancer." (PMID 39495702, 2024). "While prior research efforts predominantly concentrated on JAK/STAT3’s role in cellular processes like differentiation and proliferation, our study brought forth its hitherto uncharted regulatory role in colon cancer." (PMID 38992688, 2024). "α-Hederin was also shown to block the expression of JAK2 or activated STAT3, significantly inhibiting IL-6-induced epithelial-mesenchymal transition in colon cancer cells." (PMID 38244586, 2024). "Our data suggest that the LRRK2 G2019S mutation enhances the production of IL-1β, IL-6 and IL-11 in the colon tumor microenvironment, thereby activating the NF-κB and STAT3 signaling pathways." (PMID 38607004, 2024). "By overexpression, silencing, and immuno-precipitation of DDX58, it was demonstrated that DDX58 activates STAT3 in a colon cancer cell line." (PMID 39365797, 2024). "The continuous activation of STAT3 can significantly increases c-myc and Survivin expression, thereby accelerating the growth of colon cancer cells." (PMID 38710698, 2024). "Transfection of S100A8 or S100A9 expression vectors into colon cancer cells significantly activated NF-κB, STAT3, and ERK-MAPK, highlighting the role of S100A8/A9 as potent cancer promoters by orchestrating key connections within the signaling cascade." (PMID 38817853, 2024). "Treatment of Apcmin/+ mice with the STAT3 inhibitor BP-1-102 reduced the growth of colonic tumours via the downregulation of STAT3 activity and STAT3-dependent NF-κβ activation." (PMID 38600086, 2024). "It is also verified that miR-34c-5p stimulated cellular proliferation by regulating the SIRT6-mediated activation of the JAK2/STAT3 signaling pathway in colon cancer cells." (PMID 38185635, 2024). "The abnormality in the JAK2/STAT3 pathway is involved in the tumorigenesis of colon cancer including apoptosis." (PMID 38869738, 2024). "Stimulation of colon cancer cells with TQ reduced nuclear localization, constitutive phosphorylation, and reporter gene activity of STAT3." (PMID 38397437, 2024). "Our previous studies demonstrated the modulatory effects of new synthetic thio-chalcone derivatives in dishes on the Nrf2, NF-κB, and STAT3 signaling pathways in colon cancer cells." (PMID 39409068, 2024). "Research suggests that luteolin can suppress the growth and migration of colon cancer cells by inhibiting the IL-6/STAT3 signaling pathway." (PMID 39061884, 2024). "Our previous studies using synthetic thio-derivatives of chalcones in colon cancer cells showed that these compounds inhibit the expression of the p-STAT3 protein, and a reduction in the nuclear fraction of STAT3 binding to DNA was observed." (PMID 39409068, 2024). "STAT3 is a key participant in NETosis induced by liver inflammation, as experiments have shown that STAT3 overexpression or PMA treatment both promote the formation of NETs in the colon cancer-derived neutrophils." (PMID 39261768, 2024). "Upregulated miR-29a-5p in vitro led to increased STAT3 expression in colon cancer cells (IEC-6, HCT-116, and RAW264.7)." (PMID 38185635, 2024). "where they demonstrated a downregulation of MUC2 production by colon cancer cells due to rIL-6 or macrophage-derived IL-6 treatment in a STAT3-dependent manner." (PMID 39170608, 2024). "ETBF induces colitis, activates signaling transducer and activator of transcription 3 (STAT3), and T-helper 17 cell responses in multiple intestinal neoplasia (Min) mice with colon tumors." (PMID 39483461, 2024). "SK has been found to inactivate the IL-6/signal transducer and activator of transcription 3 signaling and decrease A disintegrin and metalloproteinase 17 expression to suppress growth of colon cancer cells." (PMID 38745186, 2024).
colon carcinoma (continued). "The curcumin analogue GO-Y030 is another diarylpentanoid reported to inhibit Notch signaling, STAT3 phosphorylation and tumor sphere formation in colon cancer stem cells, resulting in apoptosis." (PMID 38542474, 2024). "Previously, carnosol, a phytonutrient from rosemary, impedes human colon cancer by suppressing the phosphorylation of STAT-3." (PMID 39574470, 2024). "Following activation of PTK6 by DNA damage, PTK6 stimulated STAT3 in the HCT116 colon cancer cell line." (PMID 37509364, 2023). "The STAT3-mediated increase in TNFR2 expression on colon cancer cell lines was reduced by SOCS3, a cytokine-inducible STAT3 inhibitor." (PMID 36765633, 2023). "Weak activity on A4 (STAT-3 independent) colon cancer cells indicated that the compounds possibly induced STAT-3-specific inhibition." (PMID 36345416, 2023). "Several inhibitors of STAT3 determined potent anti-proliferative effects when tested against LoVo and various other human colon cancer cell lines." (PMID 38139304, 2023). "For example, propofol inhibits the development of bladder cancer and colon cancer by regulating miR-145-5p or JAK2/STAT3 signaling pathway." (PMID 37771421, 2023). "The rrPPC/siSTAT3 complexes were successfully internalized into C26 colon cancer cells, leading to STAT3 silencing." (PMID 38067351, 2023). "ROS dependent inactivation of STAT3 also mediates carnosol-induced apoptosis in human colon cancer HCT116 cells." (PMID 37386230, 2023). "This suggests that the deletion of short sequences in the STAT3 DNA-binding domain inhibits transcriptional activation and alters the recognized DNA motif, thereby affecting colon cancer development." (PMID 37020597, 2023). "A high level of active STAT3 was found in colon cancer-initiating cells, which were also characterized by the expression of ALDH and CD133 markers." (PMID 38067351, 2023). "According to a further study, Salmonella encourages the development of colonic tumors; its AvrA protein can stimulate the Wnt and STAT3 signaling pathways in colonic tumor cells." (PMID 36834525, 2023). "A colon cancer-based study reported that the inhibitory effects of formononetin were related with STAT3 and phosphatidylinositol-3-kinase (PI3K)/protein kinase B (AKT) signaling pathways." (PMID 37298670, 2023). "ALDH+/CD133+, a subpopulation of SW480, HCT116, DLD-1, and HT-29 colon cancer cells, was treated with STAT3 shRNA." (PMID 38067351, 2023). "Pancreatic, ovarian, and colon cancers have been associated with VEGF, EGFR, SRC, and JAK overexpression and STAT3 activation." (PMID 36852795, 2023). "In colon cancer, ceramide blocks cell proliferation and migration through the downregulation of IL-10, STAT3 and NF-kB expression." (PMID 38203299, 2023). "RA suppressed NF-κB and signal transducer and activator of transcription 3 (STAT3) activation in colon cancer cells in an inflammatory microenvironment." (PMID 37836581, 2023). "Hao and co-workers have shown that hyperexpression of ZNF460 is related to adverse prognosis and that it facilitates cell migration in colon cancer via the JAK2/STAT3 signaling pathway." (PMID 37057209, 2023). "The Salmonella AvrA protein stimulates the Wnt and STAT3 signalling pathways that induce the development of colonic tumour cells." (PMID 37727836, 2023). "STAT3 activity in colon carcinoma cells is triggered via interleukin-6 (IL6) or through a constitutively active STAT3 mutant promoted cancer cell multiplication." (PMID 35551547, 2022). "Studies showed that TAMs induce the epithelial–mesenchymal transition (EMT) process through the STAT3 signalling pathway to accelerate the metastasis of colon cancer, revealing the molecular mechanism between immune cells and tumour cells in colon cancer." (PMID 36372977, 2022). "Constitutive activation of STAT3 in colon cancer cells leads to cell proliferation and tumor growth." (PMID 35642021, 2022). "After adding diosgenin to treat colon cancer cells, the expression of STAT3 was significantly reduced." (PMID 35698571, 2022).